UBE4B (ubiquitination factor E4B)
Diseases named in the same sentence as UBE4B in open-access papers (continued):
Sharing a sentence is not in itself a finding about the gene and the disease.
brain tumors (4 papers, 2014 to 2022). "On the other hand, brain tumors such as medulloblastoma and ependymoma exhibit elevated protein levels of UBE4B which are often attributed to increased levels of mRNA, whereas sometimes augmentation of mRNA levels is related to gene amplification." (PMID 31878315, 2019). "The UBE4B gene has been found to be amplified at a high frequency in various types of brain tumors." (PMID 36440598, 2022).
Spinocerebellar ataxia type 3 (3 papers, 2011 to 2022). "In the Drosophila spinocerebellar ataxia type 3 model, UBE4B ubiquitinates ataxin, targeting it for proteasomal degradation." (PMID 34078905, 2021). "In animal models of spinocerebellar ataxia type 3 (SCA3) and Alzheimer's disease (AD), UBE4B facilitates clearance of ataxin 3 and APP, respectively." (PMID 36440598, 2022).
Alzheimer disease (2 papers, 2022 to 2024). A progressive, neurodegenerative disease characterized by loss of function and death of nerve cells in several areas of the brain leading to loss of cognitive function such as memory and language. "Disruption of endosomal sorting complexes required for transport (ESCRT) -mediated APP trafficking and ubiquitination by ubiquitination factor E4B (UBE4B) dysregulation contributes to Aβ accumulation in Alzheimer’s disease." (PMID 38347638, 2024).
lung adenocarcinoma (2 papers, 2022 to 2025). A carcinoma that arises from the lung and is characterized by the presence of malignant glandular epithelial cells. "In addition, UBE4B promotes lung adenocarcinoma development by enhancing cell proliferation, migration, and glycolysis through the PP2A/AKT signalling pathway." (PMID 40701960, 2025).
Machado-Joseph disease (2 papers, 2019 to 2025). "UBE4B has been found to be associated with the poly-ubiquitination of an abnormal form of ataxin-3, which has been shown to be responsible for the development of Machado-Joseph disease (MJD)." (PMID 31878315, 2019). "Indeed, functional abnormalities of UBE4B have been confirmed in several studies as a key regulatory factor of neurodegenerative diseases such as Alzheimer’s disease (AD), Machado-Joseph disease (MJD), and peroneal muscular dystrophy (CMT)." (PMID 40701960, 2025). "Interestingly, UBE4B has been found to poly-ubiquitinate an abnormal form of ataxin-3 which is responsible for the development of Machado-Joseph disease, thereby marking it for degradation by the ubiquitin-proteasome pathway." (PMID 31878315, 2019).
aneurysm (1 paper, 2020). Bulging or ballooning in an area of an artery secondary to arterial wall weakening. "Elevated expression of UBE4B may be caused by many miRNAs selected as biomarkers of AAA and lead to aneurysm expansion through inhibition of endothelial growth factor receptor (EGFR)-mediated proliferation of vascular cells by enhancing EGFR degradation." (PMID 32599769, 2020).
gastric cancer (1 paper, 2025). A primary or metastatic malignant neoplasm involving the stomach. "In this study, we identified the interaction of the U-box structural domain in UBE4B with FAT4 as an important molecular mechanism that regulates gastric cancer progression." (PMID 40701960, 2025). "The aim of this study was to reveal the functional significance of UBE4B in gastric cancer (GC) development and its important mechanism." (PMID 40701960, 2025). "The expression level of UBE4B in gastric cancer patients <60 years old was higher than that in patients ≥60 years old." (PMID 40701960, 2025). "This growth inhibition could be reversed by FAT4 knockdown, suggesting that the regulation of gastric cancer by UBE4B depends on FAT4." (PMID 40701960, 2025). "We downloaded and analysed the mRNA expression data for GC patients from the Gene Expression Omnibus (GEO) and The Cancer Genome Atlas (TCGA) databases to explore UBE4B expression in gastric cancer tissues." (PMID 40701960, 2025). "Tumour microarrays (TMAs) were used to analyse the expression of UBE4B and FAT4 in the tumour and adjacent normal tissues of 94 patients with gastric cancer, as well as the corresponding clinicopathological information." (PMID 40701960, 2025). "Therefore, the aim of this study was to investigate the expression of UBE4B in GC and its mechanism of action in the development of gastric cancer." (PMID 40701960, 2025). "Here, our findings reveal a novel mechanism by which UBE4B mediates the ubiquitination and degradation of FAT4 to promote gastric cancer progression." (PMID 40701960, 2025). "However, no study has investigated the expression of UBE4B in gastric cancer." (PMID 40701960, 2025).
leiomyoma (1 paper, 2022). A well-circumscribed benign smooth muscle neoplasm characterized by the presence of spindle cells with cigar-shaped nuclei, interlacing fascicles, and a whorled pattern. "We have previously shown UBE4B to be the most significantly downregulated gene on the 1p arm in leiomyomas harboring a 1p deletion." (PMID 36068196, 2022).
lung carcinoma (1 paper, 2019). "This potential tumorigenic role of UBE4B has been confirmed in head, neck and lung cancer cell lines." (PMID 31878315, 2019). "Upon monitoring of UBE4B expression in colon cancerous tissues, we found the same expression pattern detected in lung cancer, which is the upregulation of UBE4B ligase in malignant areas relative to the normal ones." (PMID 31878315, 2019).
lymph node metastasis (1 paper, 2025). "An analysis of the clinicopathologic findings revealed that high UBE4B expression was associated with nerve invasion (p = 0.031) and lymph node metastasis (p = 0.029)." (PMID 40701960, 2025).
neuropathies (1 paper, 2019). "Intriguingly, UBE4B is involved in a limited number of pathological conditions, which mostly represent neuropathies and cancer, whereas alterations either in the UBE4B gene or in the protein have been frequently found in various types of cancer." (PMID 31878315, 2019).
non-small cell lung carcinoma (1 paper, 2025). A group of at least three distinct histological types of lung cancer, including non-small cell squamous cell carcinoma, adenocarcinoma, and large cell carcinoma.
tumor (17 papers, 2005 to 2026). "Deletion of this region within 1p36.2-3 has been linked with the inactivation of tumor suppressors including the UBE4B ligase." (PMID 31878315, 2019). "Out of 34 tumor samples, 7 were found to have chromosome 1p36 loss, and all 7 also had loss of the UBE4B gene." (PMID 27014418, 2016). "The role of UBE4B in tumors is dual, acting as both a tumor suppressor and a tumor promoter, depending on the tumor type and cellular environment." (PMID 40701960, 2025). "The results revealed that the expression level of UBE4B was greater in tumour tissues than in adjacent normal tissues." (PMID 40701960, 2025). "In vivo animal experiments revealed that the knockdown of UBE4B inhibited tumour growth, whereas the opposite effect was observed after the overexpression of UBE4B." (PMID 40701960, 2025). "MKN45 cells overexpressing UBE4B were injected subcutaneously into nude mice, and tumour volumes were measured every 3 days to verify the effect of UBE4B on cell growth in vivo." (PMID 40701960, 2025). "In conclusion, we demonstrated that UBE4B not only promotes the growth of GC tumours in vivo but also plays a corresponding role by regulating FAT4 levels." (PMID 40701960, 2025). "Bioinformatics analysis, immunohistochemistry (IHC), western blotting, and real-time PCR were performed to detect UBE4B expression in human GC samples and GC cell lines and a mouse xenograft tumour model was established." (PMID 40701960, 2025). "The tumour volume of the UBE4B-overexpressing group was significantly larger than that of the corresponding control group." (PMID 40701960, 2025). "The tumour volume of the UBE4B knockdown group was significantly smaller than that of the corresponding control group, and the tumour volume of the UBE4B and FAT4 co-knockdown group was significantly larger than that of the group with UBE4B knockdown alone." (PMID 40701960, 2025). "In tumor cell lines, transient depletion of UBE4B results in increased levels of EGFR and activation of the downstream MAPK/ERK signaling pathway." (PMID 37754259, 2023). "In this study, we investigated the UBE4B expression, prognosis, tumor immune microenvironment, and regulatory mechanisms of HCC." (PMID 36470669, 2022). "UBE4B is a newly identified member of E3 ubiquitin ligases that appears to be overexpressed in several human neoplasms." (PMID 31878315, 2019). "In TMA samples, 26 of 43 differentiated tumor samples (61%) demonstrated increased UBE4B protein expression, compared to 24 out of 126 (19%) undifferentiated tumor samples (p < 0.0001)." (PMID 27014418, 2016). "Lower expression in cell lines was seen in KIF1B and equal levels of cell lines and stage 2 primary tumours in UBE4B, PGD and PEX14." (PMID 15740626, 2005). "In addition, the tumour weight in the control group was lower than that in the UBE4B-overexpressing group." (PMID 40701960, 2025). "UBE4B was highly expressed in most tumour samples, whereas FAT4 was expressed at low levels." (PMID 40701960, 2025). "Our results demonstrated a tumor process between UBE4B and HCC." (PMID 36470669, 2022). "Additionally, AHR, DDA1, and UBE4B protein were detected in all tissue samples analyzed from an additional cohort of brain metastases independently of primary tumor source and the presence of clinically validated HSP90‐dependent oncogenes (Table EV5)." (PMID 35174975, 2022).
tumor (continued). "The ubiquitination factor E4B (UBE4B) has been extensively explored in ccRCC tumor tissues and cell lines and may act as an oncogene in ccRCC development, apoptosis, and cell proliferation regulation." (PMID 35538487, 2022). "Moreover, according to recent findings, UBE4B interacts physically with p73a isoform in various cancer cell lines, hindering the tumor-suppressor activity of p73a by promoting its proteasomal degradation." (PMID 31878315, 2019). "Neither 1p36 nor UBE4B loss was identified in any of the remaining 27 tumor samples, suggesting that loss of UBE4B likely occurs in the majority of cases of chromosome 1p36 deletion." (PMID 27014418, 2016). "FISH for UBE4B and 1p36 deletion was performed on tumor samples." (PMID 27014418, 2016). "Therefore, UBE4B has a tumour-promoting role in GC and may be a valuable prognostic biomarker for GC patients." (PMID 40701960, 2025). "Thus, UBE4B promotes the growth of tumour cells in the body." (PMID 40701960, 2025). "In order to determine whether UBE4B gene expression was correlated with chromosome 1p36 deletion, we analyzed results from datasets in the R2 Genomics Analysis and Visualization Platform with information about tumor 1p36 status." (PMID 27014418, 2016). "For example, chromosome 1p deletions affect many potential tumor suppressors including CHD5, CAMTA1, KIF1B, CASZ1, UBE4B, and MIR34A." (PMID 35246212, 2022). "Several other putative tumor suppressors in the chromosome 1p or 11q deletion regions including CHD5, UBE4B, CADM1, and ATM, have patterns that are similar to KIF1B, where a subset of samples exhibit strong ASE in the absence of deletions." (PMID 35246212, 2022). "In addition, the tumour weight of the UBE4B knockdown group was lower than that of the control group, and the tumour volume of the UBE4B and FAT4 co-knockdown group was significantly larger than that of the UBE4B knockdown group." (PMID 40701960, 2025). "The analyzed fragments of the genes UBE4B, KIF1B, PGD, DFFA and PEX14 were not methylated in the panel of NB primary tumours and cell lines." (PMID 15740626, 2005). "The genes UBE4B, KIF1B, PGD, APITD1, DFFA and PEX14 are down-regulated in high stage NB tumours, a feature that can not be explained by CpG island methylation." (PMID 15740626, 2005). "Hence, the six genes UBE4B, KIF1B, PGD, APITD1, DFFA and PEX14 are down-regulated in high stage NB tumours, a feature that can not be explained by methylation, rather by a mechanism still remaining to be discovered." (PMID 15740626, 2005).
cancer (14 papers, 2014 to 2025). A tumor composed of atypical neoplastic, often pleomorphic cells that invade other tissues. "Ubiquitination factor E4B (UBE4B/UFD2) has been shown to be associated with the development of several cancers." (PMID 40701960, 2025). "Wip1 deprivation in different cancer cell lines increased in phosphorylated UBE4B at S669 in response to DNA damage (IR and UV)." (PMID 40175346, 2025). "The results showed that the overexpression of UBE4B or Wip1 significantly increased the colony formation rate, suggesting that both UBE4B and Wip1 promote the proliferation of cancer cells." (PMID 40175346, 2025). "In recent years, an increasing number of scholars have focused on the role of UBE4B in cancer, and studies have shown that the UBE4B gene is overexpressed or repressed in many types of cancer." (PMID 40701960, 2025). "Together, our findings indicate that the depletion of UBE4B or Wip1 suppresses cancer cell proliferation." (PMID 40175346, 2025). "Here, we investigate the dynamic patterns of UBE4B after DNA damage in several human cancer cell lines." (PMID 40175346, 2025). "Dysregulation of UBE4B has been observed in various cancers, including those of the brain, liver, breast, and nasopharynx." (PMID 40175346, 2025). "UBE4B can act as an oncogene or tumor suppressor gene in different types of cancers with opposite functions." (PMID 36470669, 2022). "OS analysis also indicated the prognostic value of UBE4B in several cancers, including BLCA, LIHC, SARC, ESCA, HNSC, and KIRC." (PMID 36470669, 2022). "Then, samples were integrated from the GTEx database and the expression levels of UBE4B in various cancers were compared." (PMID 36470669, 2022). "Our above in-situ findings from human clinical samples support that UBE4B is a potentially significant regulator of cancer progression." (PMID 31878315, 2019). "Particularly, it has been shown that gamma irradiation, a known DSB inducer, leads to increased UBE4B protein levels in various human cancer cell lines." (PMID 31878315, 2019). "In the current manuscript, we provide an overview on the roles of UBE4B/UFD2a in normal cellular function and its implication in human disorders such as cancer development." (PMID 31878315, 2019). "Only a few studies have reported oncogenic behavior of UBE4B, which relies on its forced overexpression in cancer cell lines and animal models, leading to larger tumors compared to cancer cells bearing solely the endogenous gene." (PMID 31878315, 2019). "Specifically, targeting UBE4B and its network can sensitize cancer cells to DNA-damaging agents." (PMID 40175346, 2025). "Next, we sought to determine whether there are differences in overall survival between UBE4B and Wip1 expression in human cancers." (PMID 40175346, 2025). "UBE4B is an E3 ubiquitin ligase known for its involvement in the ubiquitination and degradation of protein substrates, playing a significant role in tumorigenesis and progression across various types of cancer." (PMID 41331871, 2025). "Increasing evidence has demonstrated that ubiquitin ligase E4B (UBE4B) may be involved in the occurrence and development of various human cancers and may affect prognosis." (PMID 36470669, 2022).
cancer (continued). "The GEPIA database was used to elucidate the relationship between UBE4B expression and pathological stages in different cancers, revealing significant correlations between UBE4B expression and pathological stages of COAD (P = 0.00308), KIRC (P = 8.01 × 10-5), LIHC (P = 0.00739), and OV (P = 0.0233)." (PMID 36470669, 2022). "In this study, the expression of UBE4B was analyzed in pan-cancer using TCGA and GTEx databases." (PMID 36470669, 2022). "Additionally, UBE4B can be involved in the development of various cancers, such as renal cell carcinoma, breast cancer, and neural tube cell tumors, by regulating the ubiquitination of substrate proteins." (PMID 36470669, 2022). "Moreover, some reports indicate the contribution of UBE4B towards cancer cell survival upon DNA damage induced by factors such as chemical agents or IR." (PMID 31878315, 2019). "UBE4B has been found either overexpressed or suppressed in diverse types of human cancer." (PMID 31878315, 2019). "However, the regulation of UBE4B in relation to DNA damage in cancer is not well understood." (PMID 40175346, 2025). "Therefore, understanding how UBE4B is regulated in cancer cells in response to DNA-damaging agents could help develop new therapeutic strategies to improve the prognosis for cancer patients." (PMID 40175346, 2025). "If the function of UFD-2 is conserved and UBE4B is important for Nrf2 activity, this raises the possibility that increased levels of phase 2 detoxification enzymes may also contribute to the survival of cancer cells expressing high levels of UBE4B." (PMID 25204677, 2014).